CD4 (CD4 molecule)
Diseases named in the same sentence as CD4 in open-access papers (continued):
Sharing a sentence is not in itself a finding about the gene and the disease.
COVID-19 (continued). "Only effector memory CD4+ and CD8+ were decreased in their frequencies within the CD4+ and CD8+ T cells in patients with moderate/severe COVID-19, whereas naïve, central memory and TEMRA subpopulations remained unchanged." (PMID 35265078, 2022). "T-distributed stochastic neighbor embedding (t-SNE) analysis showed reduction of T cell numbers, including total T cells, CD4+ and CD8+ T cells in COVID-19 patients compared to healthy subjects, matched for age and sex." (PMID 35508575, 2022). "We show that both CD4+ and CD8+ antigen-specific T cell responses were reduced in children with MIS-C compared with those convalescing from COVID-19 and were similar to or lower than responses in HC." (PMID 35044955, 2022). "We report here that children with MIS-C demonstrate significantly reduced SARS-CoV-2 CD4+ and CD8+ T cell responses compared with children with COVID-19, implicating a poorer antiviral T cell response in the development of MIS-C." (PMID 35044955, 2022). "Distinct differences in the CD4+ and CD8+ T populations between a COVID-19 patient and a healthy control are shown in the representative pseudo-color dot plots." (PMID 36003367, 2022). "We defined the AIM+ cells as OX40+CD137+ for CD4+T cells and CD69+OX137+ for CD8+T cells following the method to identify SRAS-CoV-2 antigen-specific T cells in COVID-19 patients and vaccinated individuals." (PMID 35418996, 2022). "Compared to the control sample, COVID-19 had a lower ratio of T cells CD8 but a higher ratio of mast cells resting, T cells CD4 memory resting, macrophages M0, and dendritic cells resting." (PMID 36531995, 2022). "A meta-analysis of 20 publications found statistically significant decreases in total lymphocytes, CD4+ and CD8+ T-cells, and B-cells in critically ill COVID-19 patients compared to patients with moderate or mild disease." (PMID 36267156, 2022). "The results showed that the absolute counts of total lymphocytes, CD3+, CD4+, and CD8+ T cells, CD19+ B cells, and CD56+ NK cells, were significantly lower in COVID-19 patients than normal healthy controls and vaccinated subjects." (PMID 35898494, 2022). "In patients with COVID-19, the level of helper T cells (CD3 and CD4), cytotoxic suppressor T cells (CD3 and CD8), and regulatory T cells are below the normal background." (PMID 36077133, 2022). "Some studies indicated that activated CD4+CD25+CD127low Tregs were highly increased in moderate and severe COVID-19 patients, compared with healthy controls." (PMID 35497875, 2022). "Factors against getting vaccinated included living in a rural area, having a most recent CD4+ cell count check more than one year ago, having concerns about vaccine effectiveness and believing HIV medications protect against COVID-19 transmission." (PMID 36101660, 2022). "Higher numbers of effector memory like CD4+ and CD8+ cells, CD14+CD16+ monocytes, neutrophils were observed in respiratory samples of COVID-19 patients compared to the levels found in peripheral blood." (PMID 36211412, 2022). "Our systematic review and meta-analysis revealed that CD4 and CD8 T-cells are reduced in COVID-19 patients." (PMID 35572964, 2022). "In COVID-19, the function of PD-1 is still a matter of debate because some research teams have consistently reported that CD4+ and CD8+ T cells from COVID-19 patients express high PD-1 levels and are exhausted." (PMID 35860236, 2022). "In vitrol-arginine addition increased the proliferation rates of CD4 and CD8 T cells from COVID-19 patients." (PMID 35572540, 2022). "In severe COVID-19, cytokine levels (IL-6, IL-10, and TNF-), lymphopenia (in both CD4+ and CD8+ T cells), and decreased interferon (IFN) synthesis in CD4+ T cells are all related to higher cytokine levels, which are all life-threatening." (PMID 35936126, 2022). "In summary, antiviral T cells reactive against PepTivator SARS-CoV-2 Select were detectable in convalescent COVID-19 patients and these were mainly TNF-α and IFN-γ producing CD8+ and CD4+ T cells." (PMID 35480981, 2022).
COVID-19 (continued). "In COVID-19, SARS-CoV-2 specific antibodies, CD4+ and CD8+ T cells are crucial for infection resolution." (PMID 36289890, 2022). "We hereby demonstrated that CD4 and CD8 T cells from COVID-19 patients are more likely to die by apoptosis, and that blocking caspase activation using Q-VD prevents T cells from dying and enhances Th1 profiles." (PMID 35066575, 2022). "A higher total T cell count, including both CD4+ and CD8+, has been shown to be a predictor of a less severe disease and a more favorable clinical outcome in patients with COVID-19." (PMID 35160150, 2022). "We found that COVID-19 plasma exosomes significantly induced expression of cytokines and chemokines in CD4+ and CD8+ T cells as well as in CD14+ monocytes compared with treatment with plasma exosomes derived from non-COVID-19 patients or healthy donors." (PMID 36526691, 2022). "One earlier study reported a higher percentage of CD4+ T cells and DCs and lower numbers of NKT-like cells in patients two months after COVID-19 recovery compared to uninfected controls, while other cell types remained similar between groups." (PMID 35464396, 2022). "In this review, we discussed the pathology of SARS-CoV-2 infection, main pitfalls and therapeutic strategies and also the numerous data highlighting the important role of CD4+ and CD8+ virus-specific T cells during COVID-19." (PMID 36499448, 2022). "The decrease in immune cells, especially lymphocytes, CD4+ T cells and CD8+ T cells is a marker of poor prognosis in COVID-19 patients." (PMID 36443688, 2022). "demonstrating lower expression of CD3ζ-chain in CD4+ and CD8+ T cells of COVID-19 patients, and an increased T cell function in PBMC-M-MDSC co-cultures supplemented with L-arginine." (PMID 35812392, 2022). "Known markers of CD4+ T cell activation (T-bet, Ki-67, CD69, TOX, and PD1) were significantly increased in baseline COVID-19 patients compared to HD." (PMID 35012610, 2022). "Such analysis carried out in this study, has shown that the percentage of both CD38+ HLA-DR+ CD4+ and CD8+ T cell subpopulations is significantly higher in the peripheral blood of COVID-19 patients, compared to HS and VS control groups." (PMID 35898494, 2022). "To examine the absolute numbers and percentages of major T cell subsets in acute and convalescent COVID-19 individuals, we analyzed CD3, CD4, and CD8 co-expression in three groups of patients by using flow cytometry." (PMID 36146713, 2022). "SARS-CoV-2 spike-specific CD4+ cell responses, determined as expression of CD69+ and CD134+, were detected in all tested COVID-19 patients (n=15) and vaccinees 6 weeks (n=20), 3 months (n=15) and 6 months after the first vaccine dose (n=17)." (PMID 35529867, 2022). "CD4 CTL have been reported in the blood, lymph node and lungs of COVID-19 patients and in the lungs of SARS-CoV-2-infected pig-tailed macaque monkeys." (PMID 36341327, 2022). "CD4 T-cells with cytotoxic activity (CD4 CTLs) and NK-cells displayed enhanced interferon signaling and effector activation markers (GZMB, GZMH, CCL4, XCL2) in patients who succumbed to COVID-19." (PMID 35169146, 2022). "Immune-phenotyping results showed a significant decrease in the absolute count of NK cells, CD4 + T, CD8 + T, and B lymphocytes in COVID-19 patients." (PMID 35842705, 2022). "We assessed SARS-CoV-2-specific CD4+ and CD8+ T cell responses in samples from 89 acute COVID-19 patients, utilizing blood samples collected during the first wave of COVID-19 in Italy." (PMID 35806161, 2022). "The observed PD-1 expression was higher in peripheral blood CD4+ and CD8+ T lymphocytes in COVID-19 patients of all ages, compared with healthy controls." (PMID 35432324, 2022). "Our results demonstrated that Q-VD inhibited both caspase activity and PS exposure in CD4 and CD8 T cells from COVID-19 individuals." (PMID 35066575, 2022). "During the acute phase of COVID-19, SARS-CoV-2-specific CD4+ T cells appeared relatively early and increased over time." (PMID 36146622, 2022).
COVID-19 (continued). "Total CD4+CXCR5+ Tfh cells and ICOS+Foxp3-activated Tfh cells increased and ICOS+Foxp3+ Tfr cells decreased in COVID-19 patients, especially in diabetic patients and those with severe disease." (PMID 35286241, 2022). "According to the immunological mechanisms, both viral vector and mRNA COVID-19 vaccines induced a strong activation of CD8+ and CD4+ T cells, as well as the production of IFNγ and IL-2." (PMID 36177033, 2022). "A study also found that CD4+ and CD8+ T lymphocyte subsets were significantly reduced in COVID-19 patients." (PMID 36199786, 2022). "Prior to the functional assays, the effects of C-Vx on CD4+ and CD8+ T cell levels were explored in COVID-19 patients and healthy donors." (PMID 36106521, 2022). "CD4+ and CD8+ T-cell responses have also been shown to play important roles in the resolution of SARS-CoV-2 infection and the modulation of COVID-19 severity." (PMID 36388890, 2022). "T-cell exhaustion can be the fundamental driver of COVID-19 patient mortality, such as exhaustion of CD8+ T-cells and CD4+ T-cells that would have controlled the virus." (PMID 36471834, 2022). "The longitude study of T/B cell and antibody responses to COVID-19 revealed a long duration of CD8+ and CD4+ T cell memory and neutralizing antibodies against SARS-CoV-2." (PMID 35909969, 2022). "In severe COVID-19, the TCR repertoire was also broader and of low avidity, similar to the pre-existing memory CD4+ response." (PMID 35401519, 2022). "Alongside, we observed a high expression of cytokines (CCL3, CCL4, CCL5, CCL7, CCL18 and CCL20) in the CD4+ TCM, Classical monocytes and NK cells in the COVID-19 patients." (PMID 36532041, 2022). "The lymphocyte subsets of CD4+ T cells, CD8+ T cells, B cells and NK cells were also analysed in the peripheral blood of COVID-19 inpatients in this study." (PMID 36403042, 2022). "As expected, PHA induced high expression levels of intracellular IFN-γ in CD4 + and CD8 + T cells whilst co-culture with MDSCs from COVID-19 patients significantly suppressed intracellular IFN-γ." (PMID 36581679, 2022). "CD4+ and CD8+ T cell subsets participate in T-cell immunity during viral infection; alterations of these two cell subsets have been widely studied in COVID-19 and EVD." (PMID 35890044, 2022). "Both CD4+ and CD8+ memory T-cells can be detected in the blood of patients who recovered from COVID-19." (PMID 36430430, 2022). "However, it is unknown whether the post-vaccine CD4+ T cell responses seen in patients with a history of COVID-19 are due to restimulation of T cell clonotypes that were first activated during natural infection or if they are the result of new clones activated by the vaccine." (PMID 35533495, 2022). "The CD4+ cells were significantly lower, while the total number of CD4+CXCR5+ Tfh cells was significantly higher in COVID-19 patients compared to controls (p < .0001 and p = .03, respectively)." (PMID 35286241, 2022). "Further, BAL from COVID-19 convalescents had higher cytokine-producing CD8+ and CD4 T+ cells than those of blood, although paired analysis was not performed here due to the availability of the samples obtained from a previous study." (PMID 35857583, 2022). "COVID-19 vaccine–induced immunity is less robust in PLHIV, especially for persons with low CD4+ T-cell counts or unsuppressed viremia, but our results indicate that this deficit is likely not linked to cross-reactive prepandemic responses." (PMID 36220131, 2022). "We also identified significant differences in the transitional memory, stem cell memory, central and effector memory CD4+ and CD8+ T cell subsets between MIS-C and acute COVID-19 children." (PMID 36322537, 2022). "This indicates that CD4 and CD8 T cells from COVID-19 patients are more likely to die from apoptosis." (PMID 36359755, 2022).
COVID-19 (continued). "An increase in the percentage of CD38+ and HLA-DR+ memory CD4+ and CD8+ T cells was also detected in severe COVID-19 patients compared to healthy subjects in other recent studies and this correlated with poor prognosis." (PMID 35898494, 2022). "A previous study has shown a decreased number of CD4+ T cells and CD19+ B cells expressing α4β7 integrin in blood of patients with severe COVID-19, even after remission of the symptoms." (PMID 35251032, 2022). "We next evaluated the expressions of the exhaustion markers PD-1, PD-L1, CTLA-4 and TIM-3 on CD4 + and CD8 + T cells in COVID-19 patients sampled at D0 and D20 compared to HV." (PMID 35246776, 2022). "Consistent with most reports, we have observed a significant reduction in percentages of CD3+, CD4+, CD8+ T, and B cells in the peripheral blood of COVID-19 patients compared to healthy controls." (PMID 35284964, 2022). "We can conclude that dysregulated immunity of CD4+, CD8+ and Treg cells is, to an extent, maintained for the first 3 months post COVID-19, followed by a functional switch partially visible at 3-6 month." (PMID 35757700, 2022). "CD39 surface expression was increased in CD3+CD4+ and CD3+CD8+ T cells and CD3-CD56+CD16+ NK cells from COVID-19 patients compared to HC." (PMID 35173744, 2022). "SARS-CoV-2–specific CD4+ and CD8+ T cell levels were variable, especially in convalescent COVID-19, and we next sought to better understand this range of responses." (PMID 35044955, 2022). "When characterizing adaptive immunity, we found prominent decreases of pan T cells, CD4+ and CD8+ T cells in patients with moderate/severe COVID-19 independent from the necessity of HD treatment." (PMID 35265078, 2022). "As a viral infection, COVID-19 is characterized by type Th1 protective immune response, with contribution of virus-specific CD8+ cytotoxic T cells (Tc) and CD4+ helper (Th) lymphocytes, and memory T cells maintained after infection." (PMID 36614808, 2022). "In a study trial, Neidleman and colleagues performed a phenotypical analysis of SARS-CoV-2-specific T cells, i.e., both CD4+ and CD8+ ones, from a small number of patients who have recovered from mild COVID-19." (PMID 36694588, 2022). "One study examined the effect prior COVID-19 infection has on CD4+ and CD8+ T-Cell responses to COVID-19 vaccination." (PMID 35955740, 2022). "The primary objective of the study is to explore phenotypes and estimate the activity degrees of monocytes, NK cells, and CD4+ and CD8+ T cells (including the CD4/CD8 T ratio) in COVID-19 patients’ peripheral blood." (PMID 34854818, 2022). "Analysis of CD4 + T lymphocytes, CD8 + T lymphocytes, and NK cells revealed a significant decrease in the absolute count of these cells in COVID-19 patients compared to healthy controls (p < 0.0001 for all described groups)." (PMID 35842705, 2022). "The subsets of T lymphocytes, CD4+ T cells, CD8+ T cells, and CD45+ T cells were also significantly reduced in COVID-19 patients with high HA." (PMID 35304437, 2022). "Cytokine-secreting immune cells, such as CXCR3+CD4+ T cells, CXCR3+CD8+ T cells, and CXCR3+ NK cells, were shown to be elevated in severe COVID-19 patients." (PMID 35062368, 2022). "It should be emphasized that the decrease in total levels of T cells, CD3+CD4+ and CD3+CD8+ cells in COVID-19 patients was especially significant in the elderly and in patients requiring intensive care." (PMID 35216349, 2022). "It has been observed that the number of total T cells, CD4+, and CD8+ T cells was dramatically reduced in COVID-19 patients, especially in patients requiring intensive care." (PMID 34737699, 2021). "MIS-C had higher frequencies of HLA-DR+CD38+ CD4+ and CD8+ T cells compared to pediatric COVID-19, again rivaling or exceeding that observed in adult COVID-19." (PMID 33653907, 2021).
COVID-19 (continued). "The expression levels of CD4, CD25 and FOXP3 showed a significant decrease in severe COVID-19 patients’ PBMC compared to controls (p < 0.0001, p = 0.01, p = 0.007, respectively) and CD patients (p < 0.0001 for all of them)." (PMID 34895167, 2021). "Conversely, the frequencies of CD4+ effector cells differed: the amount of specific AIM+IFNγ+ and AIM+IFNγ+IL-2+TNFα+ (triple+) CD4+ T cells were lower in COVID-19-naive older participants than in COVID-19-naive young adults." (PMID 34868051, 2021). "Generally, COVID-19 vaccine candidates have induced low T cell responses in mice, with IFNγ+ responses of 0 to 2% and 0 to 1% among CD8+ and CD4+ T cells, respectively, or 1000 to 2000 SFCs/1 × 106 splenocytes by IFNγ ELISpot." (PMID 33547083, 2021). "TH1-predominant responses and balanced CD4+ and CD8+ T cell responses are less likely to induce immunopathology and are therefore preferred COVID-19 vaccine characteristics." (PMID 34591596, 2021). "Low levels of CD4+ and CD8+ T cells and B cells correlate with the severe course of COVID-19 and unfavorable outcome; the phenomenon of immune depletion mainly occurs with CD8+, to a lesser extent CD4+ T cells." (PMID 34441420, 2021). "This protective response is consistent with an observed skewing of the spike-specific CD4+ T cells towards a circulating T follicular helper (TFH) profile, which is crucial for antibody production, in convalescent COVID-19 individuals." (PMID 34113347, 2021). "A vaccine applying conserved SARS-CoV-2 epitopes that induce both memory CD8+ and CD4+ T-cell responses across different populations with various HLA allotypes might represent a promising tool to end the public health and economic burdens due to the COVID-19 pandemic." (PMID 34960205, 2021). "Evidence of T cell activation in both CD4+ and CD8+ T cells has recently been reported in COVID-19 patients." (PMID 34867933, 2021). "Some studies reported no changes in the number of B cells and NK cells while others described a drastic decrease in all major lymphocyte subsets (CD4+ T cells, CD8+ T cells, NK cells and B cells) in severe COVID-19 cases compared to mild cases." (PMID 34707619, 2021). "Lower total lymphocytes and CD4+ T, CD8+ T, B, and NK cells were found in COVID-19 patients and those with severe cases compared to mild cases of COVID-19 had lower lymphocyte subsets." (PMID 35008706, 2021). "Just like our sub-healthy individuals, PD-1 expression is increased significantly in the CD4+ T cells and CD8+ T cells of PBMCs in COVID-19 patients." (PMID 34461606, 2021). "This peptide is recognized by CD4+ T cells in 20% of unexposed individuals, more than 50% of SARS-CoV-2 convalescents, and 97% of subjects treated with the Pfizer–BioNTech COVID-19 vaccine." (PMID 34465633, 2021). "Based on the severity of COVID-19, critical cases showed lower CD3+ T cells (P < 0.0001), CD4+ T cells (p-value = 0.001), CD19+ B cells (P = 0.025), and CD20+ B cells (p-value = 0.018)." (PMID 34225645, 2021). "Our data showed that the memory CD4+ and CD8+ T cells of 94.44% and 83.33%, respectively, of the COVID-19 patients successfully underwent expansion." (PMID 33741972, 2021). "On the contrary, the relative level of CD4, CD25 and FOXP3 mRNA expression in COVID-19 patients was significantly lower than in controls (p < 0.0001, p = 0.01, p = 0.007, respectively)." (PMID 34895167, 2021). "At the same time, there are much higher frequencies of senescent phenotype TEMRA+ CD57+ CD8+ T cells but reduced antiviral cytokine production and cytotoxicity of CD4+, CD8+ T, and NK cells in patients with COVID-19." (PMID 34938296, 2021). "An immunosuppressive mTOR inhibitor drug that is designed to treat T cell (CD4+ and CD8+) dysfunction in patients with COVID-19." (PMID 33937545, 2021). "Activated phenotypes of CD4 + T cells and CD8 + T cells were found in patients with COVID-19, and markers of T cell exhaustion both in lung and circulating were upregulated." (PMID 34074305, 2021).